STAT3 (signal transducer and activator of transcription 3)
Diseases named in the same sentence as STAT3 in open-access papers (continued):
Sharing a sentence is not in itself a finding about the gene and the disease.
cancer (continued). "Among such pathways, aberrantly activated STAT3 signaling is considered an attractive therapeutic target for the treatment of many types of human diseases, including cancer." (PMID 31684051, 2019). "Since STAT3 is emerging as a target of interest for many cancers it is essential to identify novel STAT3 target genes that will help understand the pleiotropic functions of STAT3 in tumorigenesis." (PMID 30622697, 2019). "Although most of these data have been obtained from cancer cells, a few articles described the link between miRNA and STAT3 in cardiac tissue." (PMID 31220137, 2019). "The active form of STAT3 is constitutively and aberrantly activated in many types of cancers including TNBC, where it promotes tumorigenesis." (PMID 31456939, 2019). "We have chosen to investigate four genes SIRT1, FGFR2, STAT3, and RAGE which are known to be closely associated with different types of cancer and are related to pathogenetic processes." (PMID 31781300, 2019). "Inappropriate/persistent STAT3 activation is described in a number of neoplasias, including CRC, and STAT3 blockade in cultured cancer cells inhibits cell proliferation and induces apoptosis." (PMID 31361391, 2019). "Nonpeptidic small molecules able to permeate cells represent a more attractive approach to inhibit aberrant STAT3 activity in cancer cells." (PMID 31781335, 2019). "This suggest that some cancers progress through the activation of GP130/STAT3 cascade but other cancers develop through other pathways." (PMID 31139333, 2019). "Understanding the role of STAT3 in cancer has led to promising strides in the development of specific nucleotide inhibitors." (PMID 31671769, 2019). "We further revealed that ITGA2 interacted with STAT3 and up-regulated PD-L1 expression by increasing the phosphorylation of STAT3 in cancer cells." (PMID 31818309, 2019). "Accordingly, our novel discovery of CCND2 as a mediator of cancer stemness under JAK2/STAT3 activation provides a rationale for developing JAK2/STAT3 inhibitors to treat intractable cancers." (PMID 31511084, 2019). "Preclinical studies of targeting STAT3 signaling by STAT3 or JAK2 inhibitors also showed potent antitumor activity in cancers and some of the inhibitors are in clinical trials." (PMID 30755611, 2019). "Constitutive phosphorylation of STAT3 at Tyr705 has been encountered in several types of cancer cells and is responsible for the dimerization of phosphorylated STAT3 and its subsequent nuclear translocation." (PMID 31575007, 2019). "HAP NPs effectively deliver anti-STAT3 shRNA to prostate cancer cells leading to the induction of apoptosis and decreased viability of cancer cells." (PMID 31569687, 2019). "Signal transducer and activator of transcription-3 (STAT3) is continually activated in many human cancers." (PMID 31186039, 2019). "Beside cancer development, HSP27 regulation of STAT3 has recently been implicated in placental implantation." (PMID 31861612, 2019). "Among other signaling pathways, the JAK/STAT3 has been described to be involved in increasing survivin expression levels and promoting tumorigenesis after aberrant activation in cancer cells." (PMID 31412593, 2019). "Aberrant tyrosine phosphorylation of Stat3 has been detected at high frequency in diverse human cancer cell lines and tissues." (PMID 31383893, 2019). "Constitutive activation of the transcription factor STAT3 has been reported in different types of cancers, including lung, breast, and colon." (PMID 31695609, 2019). "In fact, the hyperactivation of STAT3 signaling occurs in the majority of human cancers and is correlated with a poor prognosis." (PMID 30857539, 2019). "As a point of convergence for many oncogenic signaling pathways, STAT3 is constitutively activated at a high frequency in a wide range of cancers and is a promising molecular target for cancer therapy." (PMID 31573734, 2019).
cancer (continued). "The protein survivin, a member of the inhibitor of apoptosis (IAP) family, is a target gene of the transcription factor STAT3 and is known to be crucial for the proliferation and survival of cancer cells." (PMID 30914735, 2019). "Accumulating evidence has revealed that p300-mediated RelA/p65 hyperacetylation by STAT3 is essential for NF-κB activation in several cancers, as protein hyper-acetylation in cells is activated in inflammation and cancers." (PMID 31248140, 2019). "Taken together, our results indicate that JAK2/STAT3/CCND2 signaling contributes to cancer stemness and radioresistance; thus, therapies that specifically target this pathway constitute a biologically driven strategy for enhancing the efficacy of radiotherapy." (PMID 31511084, 2019). "STAT3, regulated by Janus kinases (JAKs), is constitutively activated in most human malignant tumors, and is involved in the proliferation, angiogenesis, immune evasion and has anti-apoptotic effects in cancer cells, including HCC." (PMID 31161238, 2019). "The cross-talk between NF-κB and STAT3 drives tumor progression and promotes cancer stemness in multiple malignancies including gliomas." (PMID 30890700, 2019). "Recent evidence has demonstrated that STAT3 is upregulated in most cancers, and NF-κB enhances the STAT3-p300 interaction." (PMID 31248140, 2019). "Hyperactivation of STAT3 and STAT5 can also occur via direct mutation in these genes, which is also associated with cancer progression in patients." (PMID 31817042, 2019). "Napabucasin (or BBI608), which can inhibit gene expression driven by STAT3 and cancer stemness, is being clinically evaluated in solid cancers." (PMID 31861597, 2019). "It appears that STAT2 enhances the proliferation of cancer cells by elevating the level of IL-6/STAT3." (PMID 31569687, 2019). "Particularly, we identified three sesquiterpene lactones, costunolide, dehydrocostuslactone, and cynaropicrin, able to inhibit IL-6-induced as well as constitutive activation of STAT3 in different cancer cell lines." (PMID 31781335, 2019). "Multiple pathways including NF-κB, ERK, JNK, p38, and STAT3 regulate the expression of proliferative genes and transcription factors involved in cancer." (PMID 30990169, 2019). "Among the various stimulators of STAT3 activation, IL-6 is a key growth factor for tumorigenesis, and its production is considered as an important factor for linking inflammation to cancer." (PMID 31816985, 2019). "Mutations in STAT3 and STAT5 have been reported in patients with solid cancers, but unlike hyperactivation of the JAK/STAT pathway, STAT3/5 mutations in cancer are relatively infrequent and occur mostly in hematological malignancies." (PMID 31557897, 2019). "In accordance to the efficacy of SLNs in the delivery of STAT inhibitors, loading a STAT3 inhibitor on SLNs remarkably decreases the viability of cancer cells by stimulation of apoptosis via down-regulation of STAT3 phosphorylation." (PMID 31569687, 2019). "Mito-Stat3 suppresses ROS formation during cancer genesis, suggesting that targeting Ser727 phosphorylation and mito-STAT3 has strong potential in treating cancer." (PMID 31798458, 2019). "STAT3 has been shown to engage in mechanisms to augment NFκB activation and maintain IL-6 expression in a number of cancers and inflammatory disorders." (PMID 31226168, 2019). "The complicated involvement of STAT3 and its downstream molecules in cell fate determination has made STAT3 a convincible target in cancer therapy." (PMID 31485222, 2019). "The IL6/STAT3 signaling pathway has been suggested as an attractive target for the discovery of novel cancer therapeutics." (PMID 30674340, 2019). "We, as well as others have demonstrated that, persistent STAT3 activation in cancer cells induces mesenchymal and CSC properties, inhibits apoptosis, and maintains a more un-differentiated phenotype." (PMID 32355893, 2019).
cancer (continued). "STAT3 has also been shown to directly interact with mitochondrial DNA to contribute to Ras-dependent malignant transformation and cancer progression by amplifying electron transport chain function." (PMID 31671769, 2019). "The therapeutic efficacy of the blockade of the STAT3 signaling pathway in cancers has been extensively studied, and a number of STAT3 inhibitors have been developed." (PMID 31847229, 2019). "The cancer stemness properties are governed by many oncogenic pathways such as STAT3, NOTCH, WNT, and NANOG, which are highly dysregulated in CSCs due to genetic changes." (PMID 30709346, 2019). "Collectively, these studies have established the critical interplay between NF-κB and STAT3 in the regulation of inflammation-induced cancer." (PMID 31557902, 2019). "In the literature, Janus kinases (JAK) and signal transduction and transcription activation (STAT) proteins, particularly STAT3, are described as the most promising targets for cancer treatment." (PMID 31756890, 2019). "An increase in STAT3 activation was shown, which is related to self-renewal of cancer stem cells (CSCs)." (PMID 31126035, 2019). "STAT3 is not only capable of eliciting the expression of cancer-related genes, but also physically interacts and functionally cooperates with other oncogenic transcription factors, e.g., GLI1, promoting the aggressiveness of TNBC." (PMID 31088482, 2019). "Platinum (IV) complex, such as CPA-1, CPA-7, and IS3-295, inhibits the STAT3 DNA-binding activity leading to apoptosis in human cancer cell lines." (PMID 31781335, 2019). "Brevilin A has been reported to decrease the expression of p-STAT3 in many types of cancers such as lung, breast, and liver." (PMID 31178739, 2019). "Dysregulation of inflammatory cytokine signalling is an emerging mechanism in transformation and IL-6 is over-expressed in diverse cancers, correlating with increased STAT3 activity." (PMID 31226168, 2019). "Further, miR-665 was demonstrated to be the target of BCAR4 and subsequently activated STAT3 signaling which is an important pathway in cancer stem cells self-renewal." (PMID 30962766, 2019). "Several recent studies suggest a collaboration and cross-talk between STAT3 and NF-κB to promote the development of several cancers, including gastric cancer." (PMID 31292446, 2019). "In human cancers, STAT3 activation occurs often concomitantly with activation of the NF-κB transcription factor pathway." (PMID 31143708, 2019). "STAT3 has been demonstrated to bind to the Pdcd1l1 promoter (coding for PD-L1) to regulate its transcriptional expression in cancer cells." (PMID 31480382, 2019). "Our findings therefore indicate that ACEE inhibits lung tumor growth and metastasis by inducing apoptosis and by inhibiting the STAT3 signaling pathway in cancer cells." (PMID 30914735, 2019). "Growing evidence over the last years suggests a critical role of STAT3 as a point of convergence of various signaling pathways that are deregulated in cancer." (PMID 31781335, 2019). "Signal transducer and activator of transcription 3 (STAT3) is an oncogene, which upregulates in approximately 70% of human cancers." (PMID 31287013, 2019). "Like STAT3, STAT5 is able to modulate growth and suppression of cell death in a few cancer cell lines, notably association with the Bcl-Ab1 fusion protein in hematopoietic cancers." (PMID 30847297, 2019). "Overall, our findings suggest that ITGA2 enhances STAT3 phosphorylation by serving as the origin of the transcription and translation of PD-L1 in cancer cells." (PMID 31818309, 2019). "The data suggest the complexity of STAT3 in tumorigenicity and treatment responses of cancers with oncogenic KRAS." (PMID 31296870, 2019). "On the other hand, a significant number of HSIL and cancer tissues harboring either mixed or integrated form of HPV16 genome showed the elevated expression level of activated STAT3 (Median normalized E2: E6 ratio– 0; Median pSTAT3 expression–Strong)." (PMID 31487312, 2019).
cancer (continued). "Our results showed STAT1 levels were higher in cancer tissues #3 and #4S, while STAT3 levels were higher in cancer tissues #3, #4, and #5, but the correlation with CFH expression was weaker than that of STAT4." (PMID 30987235, 2019). "And while constitutive STAT3 phosphorylation is common in many cancers, JAK inhibitors have had limited clinical efficacy as single agents for the treatment of advanced stage solid tumors in people thus far." (PMID 31409327, 2019). "HPV positive cancer cell lines such as HeLa (HPV18 positive) retained markedly higher levels of STAT3 phosphorylation at both Y705 and S727 residues compared with the HPV negative cell lines (C33A, DoTc2)." (PMID 31470515, 2019). "These cytokines create an autocrine/paracrine stimulation leading to a sustained NF-κB activity, aberrant activation of STAT3 signaling, and increased expression of pro-oncogenic proteins known to promote a cancer stem cell phenotype such as CD44." (PMID 30890700, 2019). "STAT3 regulates genes involved in biological functions of cancer and immune cells, rendering this pathway an interesting therapeutic target." (PMID 31480382, 2019). "We have previously shown that icaritin exhibits anti-proliferative activities both in cancer cells and in cancer-stem cells through the IL-6/Jak2/Stat3 pathway both in vitro and in vivo." (PMID 30922248, 2019). "Phosphorylation of STAT3 on Ser-727 by protein kinase C in solid tumor cell lines leads to STAT3α activation, which induces expression of genes involved in cancer migration and invasion." (PMID 31861597, 2019). "Preclinical findings have demonstrated its ability to decrease the expression of STAT3 and its downstream oncogenic target genes in a broad range of cancer cells." (PMID 31731457, 2019). "STAT3-inducible up-regulation of the myeloid-related protein S100A9 enhances MDSCs production in cancer." (PMID 31480382, 2019). "Particularly, napabucasin—a cancer stemness inhibitor targeting STAT3-driven gene transcription—has stood out with its promising clinical efficacy and safety profile." (PMID 31731457, 2019). "The constant activation of STAT3 (signal transducer and activator of transcription 3) signal is a major intrinsic signal for cancer inflammation." (PMID 31028131, 2019). "The transcription factor STAT3 plays a key role in the regulation of PD-L1 expression in various cancer types." (PMID 31835799, 2019). "Several strategies have been developed to target JAK/STAT pathway in cancer, including STAT3 inhibitors and JAK inhibitors, showing a heterogeneous degree of success." (PMID 31438567, 2019). "It has been found that the STAT3 signaling pathway plays an important role in the anti-cancer effect induced by Cryptotanshinone in human TSCC." (PMID 31270251, 2019). "Xanthatin preferentially inhibited the growth of the cancer cells with constitutively activated STAT3 and p65." (PMID 30993883, 2019). "Studies showed that activity of STAT3 is closely relevant to cancer progression including proliferation, apoptosis, and metastasis." (PMID 31186039, 2019). "To confirm that STAT3 signalling was activated in epidural ADSCs in response to paracrine secretion from cancer cells, we evaluated STAT3 phosphorylation in ADSCs after the addition of recombinant IL-6, IL-11 and LIF by western blot." (PMID 31196220, 2019). "In clinical trials, STAT3 inhibition has been reported to have remarkable therapeutic effects against various cancer types." (PMID 31619200, 2019). "Due to these reasons we turned our attention to develop new STAT3 inhibitors that are easy to synthesize, selective for malignant glioma cells and have potent anti-cancer agents." (PMID 31361777, 2019). "The transcription factors STAT3 and NF-κB were also reported as the downstream factors regulated by PKCδ in cancer cells." (PMID 31126309, 2019). "STAT3 is aberrantly activated in a wide variety of cancers and regulates several biological processes during cell transformation and cancer progression." (PMID 31438567, 2019).
cancer (continued). "Specifically, STAT3 has been found to be aberrantly active in numerous cancers including leukemia, lymphoma, breast, lung and malignant brain tumors." (PMID 31361777, 2019). "STAT3 was shown to mediate cancer cell survival, proliferation, angiogenesis, and metastasis, as well as maintaining the CSC phenotypes." (PMID 31861050, 2019). "The process requires some crucial interacting factors, such as LIF/LIFr, IL6/IL6r, IL10, IL11, GP130, JAK, and STAT3, and correlated signal pathways, leading to the switch from anchorage-independent to anchorage-dependent growth, both in embryos and cancer." (PMID 30899759, 2019). "This study aimed to isolate and identify small-molecule STAT3 signaling inhibitors targeting CSCs from the ethyl acetate (EtOAc) extract of the roots of Polygonum cuspidatum and to evaluate their in vitro anti-cancer activities." (PMID 30709346, 2019). "Our results suggest that ITGA2 plays a critical role in cancer cell progression and the regulation of PD-L1 by activating the STAT3 pathway." (PMID 31818309, 2019). "By carrying out a drug sensitivity assay and several verification experiments, we determined that ITGA2 bound with STAT3 to initiate the transcription of PD-L1 by increasing the phosphorylation level of STAT3 in cancer cells." (PMID 31818309, 2019). "Studies have shown that persistent activation of the STAT3 signaling pathway plays an important role in the progression and invasion of human cancers." (PMID 31270251, 2019). "To date, few reports have investigated the relationship between miR‐125b‐5p and STAT3 in malignant tumors." (PMID 31065520, 2019). "CEA acts as a paracrine factor, activating human fibroblasts by signaling through both STAT3 and AKT1-mTORC1 pathways, promoting their transition to the cancer-associated fibroblast phenotype, and enhancing cell migration." (PMID 31614769, 2019). "In comparison to regulated expression of STAT3 and NF-κB in healthy cells, persistent restricted expression of these genes by uninterrupted activation of STAT3 and NF-κB will results in chronic inflammation and advancement of cancer cell growth." (PMID 30847297, 2019). "BLCAP with RNA editing at this site was found to lose its ability to inhibit signal transducer and activator of transcription 3 (STAT3), providing a clue that the Y/C editing site in BLCAP is associated with the function of BLCAP and the development of cancer." (PMID 30918658, 2019). "Under normal physiological conditions STAT3 activation is tightly regulated, but in cancer an increase in extracellular signaling or the development of constitutive activity results in the aberrant expression of STAT3 regulated genes." (PMID 30863721, 2019). "The level of TMF/ARA160 was found to be significantly decreased in glioblastoma multiforme tumors, in benign meningioma and in malignant anaplastic meningioma, where STAT3 is known to play an oncogenic role." (PMID 31557897, 2019). "The induction of PD-L1 expression in cancers is associated with oncogenic pathways, including the PTEN-PI3K-Akt and STAT3 pathways." (PMID 31399559, 2019). "A decreased p-STAT3 level by resveratrol led to an increase in the miR-34a level, suppressing migration and invasion of the cancer cells." (PMID 30791624, 2019). "For example, the transcription factor STAT3 is constitutively activated in many human cancers and makes big contribution in modulating cancer cell proliferation, survival, metastasis and so on." (PMID 31088372, 2019). "Previous reports have also shown that certain drugs can inhibit cancer metastasis by blocking EMT in malignant cells and reduce drug susceptibility by deactivating EMT-related pathways, including the AKT and STAT3 signaling pathways." (PMID 31575017, 2019). "In fact, inhibition of receptor tyrosine kinases including the epidermal growth factor receptor (EGFR) and HER2 in experimental cancer models can trigger feedback activation of STAT3 as a possible mechanism of resistance to targeted therapies." (PMID 31297057, 2019).